MTOR (mechanistic target of rapamycin kinase)
Diseases named in the same sentence as MTOR in open-access papers (continued):
Sharing a sentence is not in itself a finding about the gene and the disease.
cancer (continued). "Our results showed significant dose-dependent inhibitions in the phosphorylation levels of the PI3K, ATK, and mTOR proteins in the cancer cell lines upon treatment with AP extract." (PMID 37332348, 2023). "Inhibiting mTOR is responsible for the inhibition of cell growth, cell cycle progression, cell proliferation, and cancer arrest." (PMID 36850263, 2023). "The overexpression of ABC transporters has been noticed in a variety of cancer cell lines treated with mTOR inhibitors." (PMID 37779156, 2023). "AMPK and mTOR negatively regulate tumor suppressor factors, leading to the induction of autophagy and tumor suppression in the early stage of cancer." (PMID 36814212, 2023). "The phosphoinositide 3-kinase (PI3K)/protein kinase B (Akt)/mammalian target of rapamycin (mTOR) (PI3K/Akt/mTOR) pathway is one major deregulated pathway in various types of cancer." (PMID 37047624, 2023). "Large numbers of reports have found that PI3K/Akt/mTOR pathway is abnormally activated in the cancer environment and plays a key regulatory role in the proliferation and apoptosis of cancer cells." (PMID 36768602, 2023). "A hallmark of numerous cancers is a reduction in PTEN resulting in increased phosphorylation of AKT and activation of AKT/mTOR-regulated pathways." (PMID 37665633, 2023). "Overactivation of the RAF/MEK/ERK and phosphatidylinositol‐3‐kinase (PI3K)/protein kinase B (AKT)/mechanistic target of rapamycin (mTOR) pathways enhances growth, survival, and metabolism of cancer cells." (PMID 37250144, 2023). "Rapamycin has been suggested as a potential therapy for AD, and other blockers of the mTOR pathway, such as everolimus, are already approved therapies for certain types of cancer." (PMID 37373106, 2023). "Herpesviral cancer shows a unique mTOR-dependent transcriptional program executing rapamycin sensitivity." (PMID 37602330, 2023). "Further clinical trials encompassing a broader range of cancer types and larger patient cohorts are necessary to determine the efficacy of combining platinum drugs with PI3K/mTOR inhibitors and their potential to improve the outcomes of cancer patients." (PMID 37445831, 2023). "The mammalian target of rapamycin (mTOR) kinase is a proficient regulator of protein synthesis that connects nutrient sensing to cell growth and is frequently observed in cancer." (PMID 36768977, 2023). "The PI3K/AKT/mTOR pathway can be activated by PROK1, which is associated with almost all human cancers." (PMID 37070074, 2023). "Rapamycin (a prototype mTOR inhibitor) was clinically approved for treating various cancer types including metastatic renal cell carcinoma, pancreatic neuroendocrine cancer, and advanced breast cancer." (PMID 37631380, 2023). "AZD 2014, an mTOR inhibitor, has been reported as an anti-proliferative drug against various cancers." (PMID 37654606, 2023). "LKB1 is a negative regulator of the mammalian target of rapamycin (mTOR) pathway, often inactivated in many human cancer types." (PMID 36969070, 2023). "Intriguingly, previous research has reported the efficacy of MRT67307 and MRT68921 towards ULK1 and ULK2, which repress autophagy upon mTOR suppression and persuade apoptotic behavior in cancer cells." (PMID 37893079, 2023). "Previous work indicates that α7 nAChRs engage mTOR during development, inflammation, and cancer progression." (PMID 37454238, 2023). "Several genes have been reported to influence cell cycle, apoptosis, migration, and invasion via the PI3K/AKT/mTOR signaling pathway in cancer." (PMID 37644594, 2023). "We asked about signal transducers implicated in Sema6C-dependent activation of ERK, mTOR and YAP, accountable for the observed promotion of cancer cell growth and resistance to metabolic stress." (PMID 37002363, 2023). "Overall, these studies using mTOR-based combination therapies have suggested that using mTOR inhibitors with other anti-cancer agents to overcome the limitations facing these regimens when using alone." (PMID 37513916, 2023).
cancer (continued). "Fisetin has been shown to be effective against PI3K expression, AKT phosphorylation, and mTOR activation in various cancer cells, including prostate cancer, melanoma, breast cancer and colorectal cancer." (PMID 37626424, 2023). "There are limited cases published about switching from CNI-based immunosuppression to mTOR inhibitors in transplanted patients with malignancy." (PMID 37200246, 2023). "Stem cell upregulation by RiBi suggests that the mTOR pathway is overactivated in cancer stem cells (CSC)." (PMID 38002277, 2023). "Inhibit the expression of PDCD4 in macrophages, activate PI3K/AKT/mTOR signaling pathway, and induce the polarization of M2 macrophages, thus promoting cancer metastasis." (PMID 38188683, 2023). "These consistent findings suggested that upregulation of PI3K/AKT/mTOR signaling probably promoted radioresistance in cancers." (PMID 37802999, 2023). "The PI3K/Akt/mTOR signaling pathway exhibits excessive activation in different types of cancer, which has been fully confirmed." (PMID 37875983, 2023). "By controlling aerobic glycolysis, overactivated PTEN/PI3K/Akt/mTOR promotes cancer metabolic conversion and tumor cell proliferation." (PMID 37781694, 2023). "From a molecular standpoint, circRNAs are largely implicated in gliomas in a number of cancer-related pathways, including MAPK, PI3K/AKT/mTOR, and Wnt." (PMID 37833993, 2023). "This reprogramming is shared by other types of cancer and it is commonly associated with the activation of the PI3K/AKT/PTEN/mTOR survival pathway." (PMID 37147361, 2023). "Numerous bitter phytochemicals exhibit the ability to inhibit the mTOR signaling pathway, thereby influencing skin aging, inflammation, and cancer." (PMID 38248322, 2023). "AMPK is the downstream component of LKB1, and it is activated and involved with the regulation of mammalian target of rapamycin (mTOR) activity, which frequently alters its signaling pathway in cancer." (PMID 37491250, 2023). "It has been shown that targeting gefitinib and everolimus can inhibit the activation of the PI3K/AKT/mTOR signaling pathway, thereby blocking cancer cell cycle progression and promoting apoptosis in TNBC cells." (PMID 37641116, 2023). "Other early phase I trials using PI3K, AKT and/or mTOR as monotherapies for PDAC have been disappointing for RAS-mutant cancers." (PMID 37686543, 2023). "The PI3K/AKT/mTOR pathway is frequently dysregulated in different cancer types with consequences in cell proliferation, survival, migration and invasion." (PMID 36994107, 2023). "One of the most common types of genomic flaws in cancer is the aberrations in the PI3K/AKT/mTOR pathway." (PMID 36244040, 2023). "Activated Akt/mTOR pathway is a uniform finding in cancer, whereas its significance in haematologic malignancies is highlighted by the plethora of inhibitors with promising therapeutic efficacy." (PMID 37223600, 2023). "The mutations in helical and kinase domains lead to increased PI3K activity and the activity of PI3K has downstream effects on the AKT and mTOR pathways that control cell cycle and metabolism in cancer progression." (PMID 37715134, 2023). "Several reports support that there is an aberrant activation of the mTOR signalling pathway in cancer." (PMID 37513916, 2023). "In vitro, EA significantly decreased cancer cell proliferation, migration, and invasion, and this effect has been associated with decreased phosphorylation of the members of PI3K/AKT/mTOR/STAT3 signaling pathway." (PMID 38002335, 2023). "The mTOR signaling is believed to be an essential inducer for HCC development and progression, and targeting mTOR is thought to be a promising strategy for cancer therapy." (PMID 37133437, 2023). "Deregulation within the mTOR pathway is a commonly identified alteration in human cancers, as it is involved in cell growth and proliferation, thereby suggesting its role in the pathogenesis of BHDS." (PMID 37273290, 2023).
cancer (continued). "Inhibition of the PI3K-Akt-mTOR signaling pathway is known to suppress glycolysis and potentiate the anti-cancer effect of chemotherapy." (PMID 37631380, 2023). "The mammalian target of rapamycin (mTOR) signaling pathway plays a key role in cell growth, metabolism, and apoptosis in cancer cells, and dysregulated mTOR signaling contributes to NET development." (PMID 38067279, 2023). "Owing to these aspects, the mTOR signaling pathway has become a substantial target for cancer therapy." (PMID 37060095, 2023). "Pathway analysis identified enrichment in genes involved in mTOR signaling, cancer cell death and survival, energy metabolism pathways and oxidative phosphorylation (see “Discussion”)." (PMID 36572750, 2023). "These components can also be used to target cancer-progressing autophagy regulators like Beclin-1, mTOR, NFkB, Erk, Akt, and ROS." (PMID 37893079, 2023). "The PI3K/AKT/mTOR signaling pathway, the most prevalent cancer activation pathway, results in proliferation and a host of other malignant biological behaviors in tumor cells." (PMID 37641116, 2023). "One of the most common events in human cancer is the activation of the PI3K/AKT/mTOR signalling pathway." (PMID 37050317, 2023). "During cancer cell development and tumorigenesis, the up-regulation of Akt/mTOR signaling occurs by either carcinogens or several genetic mutations of upstream regulators." (PMID 36721812, 2023). "First, metformin directly activates AMPK, thereby inhibiting the downstream Akt/mTOR signalling pathway and resulting in the generation of cancer cells." (PMID 36915376, 2023). "Reactivation of receptor tyrosine kinases (RTK) has been described as a mechanism of intrinsic resistance to targeted therapies in a variety of cancers, including inhibitors of mTOR." (PMID 36650715, 2023). "The serine/threonine kinase mammalian target of rapamycin (mTOR) is a key regulator of cellular metabolism and a key driver of proliferation for many types of cancer." (PMID 37786686, 2023). "COSMIC database analysis shows overexpression of mTOR in the skin (8.25%), urinary tract (8.33%), and ovary (9.77%) cancers, and downregulation in central nervous system cancers (13.06%)." (PMID 37513916, 2023). "Many research results indicate the efficacy of mTOR inhibitor monotherapy in some types of cancer; however, preclinical studies demonstrate strong rationales for combinatorial treatment with mTOR inhibitors and other drugs." (PMID 37097377, 2023). "Mammalian target of rapamycin (mTOR) signalling plays a critical role in cellular functions for normal and cancer cells." (PMID 36302993, 2023). "The glucocorticoid antagonist RU486 and the PI3K/mTOR inhibitor BEZ235 were also reported to re-sensitize resistant cancer cells to standard chemotherapeutic agents." (PMID 37296848, 2023). "Through functional enrichment analyses, we identified WDHD1 as a key participant in cell cycle regulation and DNA damage repair processes while also being closely associated with several pathways associated with cancer, including E2F, MYC, and mTOR signaling." (PMID 37759234, 2023). "VP can also affect tumor cell proliferation, drug resistance, and tumorigenicity through regulation of the Wnt, PI3K, Ras, mTOR, and NF-κB signaling pathways in various cancer cells." (PMID 36983079, 2023). "The mammalian target of rapamycin (mTOR) is a serine-threonine kinase that acts as a central mediator of translation and plays important roles in cell growth, synaptic plasticity, cancer, and a wide range of developmental disorders." (PMID 37741456, 2023). "The AMPK activation and mTOR suppression resulted in both survival and proliferation failures of the cancer cells." (PMID 36982245, 2023). "The Raf/MEK/ERK and PI3K/PTEN/Akt/mTOR pathways interact to regulate cancer cell growth and sensitivity to therapies." (PMID 38028209, 2023).
cancer (continued). "Hesperetin activates AMPK in HepG2 cells, which can also activate autophagy through the AMPK/mTOR pathway to prolong the survival of specific dormant polyploidy giant cancer cells." (PMID 36826047, 2023). "mTOR is the major signalling pathway involved in the development of resistance to already-existing cancer therapies." (PMID 37513916, 2023). "Physiologically, the activity and homeostasis of the PI3K/AKT/mTOR pathway are strictly controlled by regulatory mechanisms; nevertheless, this pathway can be constitutively activated in several cancers." (PMID 36765661, 2023). "The PI3K/AKT/mammalian target of rapamycin (mTOR) signaling pathway is one of the most potent signaling pathways that are abnormally activated in various human cancers." (PMID 37370314, 2023). "Cancer cells recruit mRNAs and ribosomes and effectively utilize unfolded protein response and mTOR signaling pathways to up regulate protein synthesis leading to improved tumor cells tolerability and pathogenesis." (PMID 37483794, 2023). "Oncogenes and signaling pathways, such as the mTOR pathway, play vital roles in regulating protein synthesis and promoting cancer cell survival." (PMID 37885035, 2023). "By influencing cell survival, proliferation, and migration, the aberrant triggering of the PI3K/AKT/mTOR signaling pathway can result in a malignant phenotype of cancer cells and chemotherapy resistance." (PMID 36983711, 2023). "mTOR is involved in the regulation of numerous cellular functions and mTOR hyperactivation is frequently observed in various types of cancers contributing to cell proliferation, tumour initiation and progression." (PMID 36983607, 2023). "The AKT/mammalian target of rapamycin (mTOR) signaling pathway is essential for cell growth and survival in cancer." (PMID 36609277, 2023). "One of the key pathways regulated by KRAS is the PI3K/Akt/mTOR pathway, which plays a critical role in lipid metabolism and is frequently dysregulated in cancer." (PMID 38020549, 2023). "Although the mechanism of mTOR inhibition for anti-aging or cancer therapy is complicated and sometimes confusing, it is believed that mTOR inhibition is generally beneficial for anti-aging and anti-cancer." (PMID 37049920, 2023). "The mTOR signaling pathway is active in most human cancers, where it drives cell growth, proliferation, and cancer metabolism." (PMID 37887348, 2023). "Understanding the complex interactions between the PI3K/Akt/mTOR and Hippo pathways can provide insight into disease states, such as cancer and inflammation, and the development of targeted therapies." (PMID 37175637, 2023). "mTOR, a master regulator of energy homeostasis, plays a crucial role in coordinating cancer cell proliferation and growth." (PMID 36864505, 2023). "The downstream product of AKT is mTOR, and phosphorylated mTOR is able to promote cancer cell proliferation, migration, and invasion." (PMID 37910338, 2023). "The receptor tyrosine kinase EGFR regulates the activity of pro-oncogenic pathways including the mitogen activated protein kinases (MAPKs) ERK1/2 and mammalian target of rapamycin (mTOR), which both promote cancer cell proliferation." (PMID 37696458, 2023). "EpCAM was closely associated with various vital signaling pathways as Wnt, transforming growth factor beta (TGF-β)/SMAD, EpEX/EGFR, and PI3K/Akt/mammalian target of rapamycin (mTOR) which regulate cancer cell adhesion, proliferation, invasion, and survival." (PMID 37457288, 2023).
cancer (continued). "Canagliflozin strongly inhibits oxidative phosphorylation and reduces ATP production, resulting in the inhibition of mTOR, which suppresses cell proliferation, inhibits the cell cycle in the G1 phase, and induces apoptosis in cancer cells." (PMID 37047011, 2023). "In various cancers, including ovarian cancer, FDFT1 is associated with invasion and activates cancer cell metastasis through MMP1, CD44, and AKT/mTOR/HIF1α signaling." (PMID 37107644, 2023). "It creates a protective mucosal barrier that prevents host cell infection, activates intracellular signaling pathways such as Ras/MAPK, JAK/STAT, and PI3K/Akt/mTOR, and promotes cancer cell adhesion, proliferation, differentiation, migration, and angiogenesis." (PMID 37457288, 2023). "The PI3K/AKT/mTOR signalling pathway is one of the key intracellular signalling pathways that can undergo abnormal activation in most cancers." (PMID 37489050, 2023). "The KEGG pathway analysis of the DEGs showed that the mTOR signaling pathway, microRNAs in cancer, and PI3K/AKT signaling pathway were most significantly enriched." (PMID 37391802, 2023). "The PI3K/AKT/mTOR signaling pathway is important in driving tumorigenesis and the progression of cancer cells." (PMID 37259304, 2023). "Based on what has been learned from previous studies, controlling the PI3K/Akt/mTOR pathways can affect how well cancer cells can move and spread to nearby tissues." (PMID 37743502, 2023). "More importantly, the NaB treatment is correlated to the mTOR-dependent ferroptosis and consequent tumor growth, implicating the potential clinical applications of NaB for future cancer treatments." (PMID 37185889, 2023). "To find if the suppression of the mTOR pathway can synergistically increase the death of cancer cells with chemotherapy drugs, we cultured TCam-2 cells with different concentrations of carboplatin and mTOR inhibitors." (PMID 36969070, 2023). "Excessive autophagy induces cancer cell death through the PI3K/AKT/mTOR pathway, which plays different roles in autophagy and apoptosis of CRC." (PMID 37373349, 2023). "During cancer development, alterations in the PI3K/AKT/mTOR pathway are mainly due to PIK3CA and AKT mutations, RTKs overexpression or PTEN loss." (PMID 36672617, 2023). "Further, based on information reported in the cBioPortal for cancer genomics portal, the genes coding for mTOR protein and Raptor (mTORC1 complex activating protein) proteins do not present mutations in MCF-7 or AGS cells." (PMID 37298236, 2023). "Autophagy regulators, i.e. mTOR and AMPK, are destructively modulated during cancer initiation through tumour-suppressing factors, which cause autophagy initiation." (PMID 36865478, 2023). "Our results demonstrate that circATP9A directly binds with HuR to increase NUCKS1 expression, subsequently activating PI3K/AKT/mTOR signaling and promoting cancer progression." (PMID 38049814, 2023). "Treatment of these cells with BEZ235, a dual inhibitor of mTOR and PI3 kinase, and everolimus, an allosteric mTOR inhibitor, resulted in reduced viability and proliferation of cancer cells." (PMID 36969070, 2023). "Currently, more than 50 PI3K or dual PI3K/mTOR inhibitors are being developed and tested in cancer therapies." (PMID 36994107, 2023). "Several preclinical and clinical studies reported the potent anticancer efficacy of curcumin via targeting multiple signaling pathways, including the PI3K/Akt/mTOR pathway involved in cancer development and progression." (PMID 37047624, 2023). "Several studies proved that HDAC inhibition results in inactivation of the mechanistic target of rapamycin (mTOR), thus promoting autophagy, while acetylation is described as a mechanistic switch in favor of anti-cancer processes in HCC and CCA in vitro." (PMID 37686598, 2023). "It has been reported that JQ1 suppresses tumor growth through the regulation of the PI3K/AKT1/mTOR pathway in several cancer models, including GBM." (PMID 37108181, 2023).